RNU4-21P (RNA, U4 small nuclear 21, pseudogene)
Gene: Small nuclear RNA gene on chromosome 1 (229,535,064 to 229,535,189, reverse strand). Ensembl gene ENSG00000199672.
Homologues: Orthologues: chimpanzee U4 (98% identical), macaque U4 (93% identical). Paralogues in human: RNU4-42P (78% identical), RNU4-68P (76% identical), RNU4-84P (76% identical), RNU4-76P (75% identical), RNU4-40P (74% identical), RNU4-41P (74% identical), RNU4-67P (74% identical), RNU4-7P (74% identical), RNU4-12P (73% identical), RNU4-16P (72% identical), RNU4-31P (72% identical), RNU4-13P (71% identical), and 80 more.